CRP (C-reactive protein)
Diseases named in the same sentence as CRP in open-access papers (continued):
Sharing a sentence is not in itself a finding about the gene and the disease.
infection (continued). "Routine monitoring includes vital signs, bowel function, urine output, and when indicated, inflammatory biomarkers such as C-reactive protein or procalcitonin to monitor for early signs of infection or systemic inflammation." (PMID 40863205, 2025). "On the other hand, a normalizing or low CRP in the late postoperative course has high negative predictive value for complications —in other words, if CRP drops below certain cut-offs by day 4–5, the likelihood of an occult infection is low." (PMID 41153812, 2025). "Infection status was evaluated by monitoring C-reactive protein (CRP) and white blood cell (WBC) levels." (PMID 40760640, 2025). "We compared and evaluated these novel biomarkers for infection against current commonly used biomarkers CRP and Procalcitonin." (PMID 40523137, 2025). "Lastly, C-reactive protein (CRP), synthesized by the liver, is an important immune protein used as a marker in blood tests to evaluate inflammation and infection." (PMID 40150672, 2025). "Rigorous prospective validation in consecutive ED patients with suspected infection, including head-to-head comparison with established biomarkers procalcitonin and C-reactive protein, is essential before any clinical consideration." (PMID 41488103, 2025). "The proportion of LTA+/LPS+ EVs in plasma increased with prolonged infection time, aligning with the temporal patterns of early inflammatory markers IL‐6 and CRP." (PMID 40903799, 2025). "A secondary rise in CRP after an initial decline has been proposed as a potential indicator of infection." (PMID 41226908, 2025). "These patients exhibited substantial symptoms of AT, clear clinical signs of infection, and markedly elevated C-reactive protein and neutrophil levels, suggestive of bacterial infection." (PMID 40560509, 2025). "Serum ferritin and C-reactive protein (CRP) levels were measured during afebrile, infection-free periods." (PMID 41561495, 2025). "Serial measurements of C-reactive protein (CRP) are often taken in hospitals to assess recovery from infection, but their utility remains debated." (PMID 40764898, 2025). "Comparison of mean leukocyte, CRP, and neutrophil values at infection according to oncological diagnosis." (PMID 41024922, 2025). "Eight of eleven MSIS-cleared joint replacements (73%) clustered with culture-positive active infections despite normal ESR, CRP, and scant synovial neutrophils revealing the synovial inflammatory signature of dormant infection." (PMID 41387890, 2025). "Previous studies, including our development of CRP centile reference charts for suspected bloodstream infections (BSI), suggest variability in CRP responses across infection types." (PMID 40764898, 2025). "Quercetin treatment successfully reduces the levels of biomarkers indicative of tissue inflammation and infection, such as ferritin, lactate dehydrogenase, D-dimer, and C-reactive protein (CRP)." (PMID 39967658, 2025). "CRP is an infection-related biomarker and rises sharply when the body is infected by inflammation or suffers from tissue damage." (PMID 40678655, 2025). "Conversely, CRP represents an acute-phase protein produced by hepatic tissue in response to inflammatory processes, infections, or tissue damage." (PMID 40731765, 2025). "Amongst patients prescribed SAT in our study, a factor associated with a higher treatment failure was elevated CRP at presentation, a feature associated with failure of PJI treatment in general and likely reflecting the burden of infection on presentation." (PMID 40261077, 2025). "The properties of PCT are similar to those of CRP, i.e., it increases earlier, is more specific, and its levels are correlated with the severity of infection." (PMID 40217585, 2025). "Due to the delayed increase in CRP levels as a response to infection, CRP has low sensitivity within the first day of life." (PMID 40310124, 2025).
infection (continued). "The authors concluded that a clinical local visual discharge, a fever >38 °C, and local/persistent pain were more informative indicators of postoperative infection complications than the measured evolution of CRP levels." (PMID 40565868, 2025). "Postoperative laboratory tests showed marked decreases in infection markers including white blood cells, neutrophils, and C-reactive protein (CRP)." (PMID 41040639, 2025). "This difference between early and late infection phases was also reflected in CRP spike differences and PCT spikes across the four groups." (PMID 39562716, 2025). "Elevated serum C-reactive protein levels and erythrocyte sedimentation rate before surgery suggest the possibility of infection." (PMID 40364920, 2025). "A significant difference in CRP between postoperative day 3 and 7 can be used as a reliable predictor for infection." (PMID 40156733, 2025). "Its diagnostic advantage lies in its ability to rapidly reflect early neutrophil activation and immune initiation at the onset of infection, enabling earlier detection than conventional markers such as CRP and ESR." (PMID 41459156, 2025). "Studies in humans have shown that the ICIS is potentially useful for the prediction of infection and its severity in critically ill patients, and that it serves as a reliable marker with comparable or higher sensitivity and specificity than CRP and PCT." (PMID 41301983, 2025). "This mechanistic understanding was supported by studies showing that patients with low PNI have higher levels of inflammatory markers like CRP and PCT, which correlated with increased infection risk." (PMID 41229539, 2025). "Our data suggest that if CRP remains > 100 mg/L beyond about postoperative day 4, the index of suspicion for infection should rise." (PMID 41153812, 2025). "In terms of laboratory data, our study found that the children's infection indicators were significantly elevated, such as peripheral blood white blood cell count, C-reactive protein, and procalcitonin, consistent with literature reports." (PMID 40356779, 2025). "C-reactive protein, sedimentation rate, D-dimer, and fibrinogen values were statistically significantly higher in the deep-seated infection group." (PMID 40868411, 2025). "C-reactive protein is an acute-phase protein secreted by the liver in response to infection, inflammation, or tissue injury, induced by pro-inflammatory cytokines." (PMID 40458091, 2025). "The infection also affected biochemical parameters, with an effect of day versus treatment on C-reactive protein, creatine kinase, and cholinesterase, major in infected cows." (PMID 40005520, 2025). "C-reactive protein (CRP) is an acute phase reactant and inflammatory protein, often used as a fast and cost-effective marker of infection." (PMID 41433251, 2025). "C-reactive Protein (CRP) plays a crucial role as an acute-phase protein produced by the liver in response to inflammation, infection, or tissue injury." (PMID 40569986, 2025). "We also identified factors associated with severe infection in children with INS, and these included increased levels of WBC, CRP, and creatinine, and use of more types of immunosuppressants." (PMID 41291834, 2025). "Data analysis and synthesis were conducted using a structured approach to evaluate the diagnostic accuracy of CRP, PCT, WBC, and NLR in detecting early post-surgical infections across various surgical specialties." (PMID 40342430, 2025). "However, unmeasured confounders, such as socioeconomic status; lifestyle factors; or other infections and diseases, such as malignant diseases, acute and chronic aseptic inflammation, and miscellaneous conditions that may increase CRP levels, could still have influenced the observed associations." (PMID 40051567, 2025). "CRP generally begins to increase 6-8 h after infection, peaks within 48 h, and lasts longer than SAA during the inflammatory process." (PMID 40171163, 2025).
infection (continued). "Infections significantly alter the levels of IL-6 and CRP in the body, proving that both biomarkers can indicate an inflammatory response due to infection, but they remain unaffected by smoking habits." (PMID 40242671, 2025). "Previous studies have delineated that CRP remains at a high level during the anti-infection process and cannot predict antimicrobial efficacy." (PMID 40046191, 2025). "In this infection-free cohort, the reductions in CRP and ESR at both the 4-week and 3-month timepoints remained significantly greater in the combined anticoagulation group compared to the control group (all P < 0.05)." (PMID 41403446, 2025). "In the present study, the infection led to a significant increase in CRP on the fourth day post-infection, suggesting the inflammation in the lungs as revealed by the histopathological analysis." (PMID 40777688, 2025). "CRP exhibits a delayed rise, typically 6-12 hours after the onset of infection, and a short half-life of 24-48 hours." (PMID 40970024, 2025). "Surprisingly, CRP levels remained unchanged after infection, while SAA1 levels significantly decreased." (PMID 40572197, 2025). "In PHC in Scandinavia, point-of-care (POC) tests for C-reactive protein (CRP) are widely used for various infections." (PMID 39460385, 2025). "It is recommended to closely monitor immune markers (e.g., IL-6, CRP) during the early stages of infection and to collaborate with specialists in neurology, infectious diseases, and immunology to develop individualized treatment plans." (PMID 40264651, 2025). "CRP, though indicative of systemic inflammation, exhibits limited specificity in distinguishing infection sources (e.g., bacterial vs. parasitic etiology) or disease progression stages in PLA patients." (PMID 40703270, 2025). "The area under the ROC curve for the SOFA score at the time of the burn injury to predict infection was 0.323, for lactate at the time of the burn to predict infection was 0.371, and for CRP at the time of the burn to predict infection was 0.330." (PMID 40802437, 2025). "Studies that examine inflammatory biomarker levels often exclude children with an infection that coincides with the time of blood collection because levels of IL-6 and CRP increase in response to acute infection but return to baseline afterwards." (PMID 40605248, 2025). "For instance, elevated preoperative CRP levels are an independent predictor of postoperative infection in arthroplasty patients." (PMID 40746820, 2025). "Bloodstream infections and CRP spikes were analysed for both early (until day 100 after alloHCT) and late events (after day 100)." (PMID 39562716, 2025). "Conversely, the inverse correlation between CRP and infection status is likely explained by corticosteroid and anti-inflammatory use, which suppress acute-phase reactants." (PMID 40869330, 2025). "ICIS not only provides accurate detection of infection but also offers a faster and cost-effective alternative to the traditional biomarkers CRP and PCT." (PMID 40471473, 2025). "Patients with well-controlled HbA1c levels (less than 7%) exhibited accelerated CRP normalization (12.5 days), a reduced incidence of infection recurrence, and expedited bone healing (10.5 weeks)." (PMID 40283230, 2025). "In pediatric intensive care units in emergency situations, POCT for biomarkers such as procalcitonin (PCT) and C-reactive protein (CRP) helps clinicians to judge the severity of infection and decide on antibiotic stewardship." (PMID 41246697, 2025). "In response to injury or infection, CRP levels in the bloodstream can surge from baseline values of less than 1 μg/mL within 48 h." (PMID 39940408, 2025). "ICIS has been assessed in various patient cohorts, which demonstrated its potential for predicting infection more effectively than CRP and PCT, like our results." (PMID 40471473, 2025).
infection (continued). "This systematic review evaluates the diagnostic accuracy of C-reactive protein (CRP), procalcitonin (PCT), white blood cell count (WBC), and neutrophil-lymphocyte ratio (NLR) in identifying early post-surgical infections across various surgical specialties." (PMID 40342430, 2025). "We next determined the functional contribution of CRP against Sp23F infection by comparing the early clearance of Sp23F between wild-type (WT) and CRP-deficient (Crp−/−) mice in the first 30 min post i.v. inoculation of 106 colony forming unit (CFU) bacteria." (PMID 41214213, 2025). "All reoperations for infection in this cohort had CRP >40 mg/L (well above the recommended cutoff) and organisms were isolated on intraoperative cultures." (PMID 41399624, 2025). "At the cellular level, IVM imaging also confirmed the critical role of C3 and the C3 receptors in CRP-based KC capture of Sp23F at the high infection dose." (PMID 41214213, 2025). "Though more commonly used as a marker of inflammation or infection, CRP has been shown to have close links with nutrition, especially in acute disease." (PMID 40964588, 2025). "CRP is an acute-phase reactant synthesized by the liver, with levels significantly elevated during inflammation, infection, and tissue damage." (PMID 40937117, 2025). "This study used serum infection markers (CRP, PCT, NEUT%) to screen for patients infected with Klebsiella pneumoniae, avoiding bias caused by bacterial colonization." (PMID 39975685, 2025). "CRP is an acute-phase reactant whose concentration significantly rises during inflammation, infection, or tissue damage." (PMID 40469280, 2025). "Similar results were reported in another study, confirming that elevated CRP levels are infection severity- and type-dependent." (PMID 41464835, 2025). "CRP is produced by the liver when inflammation or infection is present; therefore, higher levels often reflect the body’s reaction to an infection." (PMID 41357512, 2025). "First, laboratory and physical findings of systemic inflammation, including elevated C-reactive protein and white blood cell count, fever, and marked decrease in the level of consciousness, are rather suggestive of severe infection." (PMID 41527640, 2025). "CRP, the most common inflammatory marker, rises rapidly following inflammation or infection due to the release of cytokines and interleukins that stimulate the liver to synthesize and release CRP." (PMID 40364829, 2025). "In our study, CRP > 100 mg/L beyond day 4 was frequently observed in patients who ultimately were diagnosed with infections, which is congruent with these reports (even though our sample size limited the statistical power)." (PMID 41153812, 2025). "Laboratory tests, including C-reactive protein (CRP) and procalcitonin, are performed to detect early signs of infection or systemic inflammation." (PMID 40863205, 2025). "After three weeks of intensive antimicrobial therapy and management of complications, infection markers (procalcitonin, C-reactive protein (CRP), white blood cell counts) normalized." (PMID 41221291, 2025). "In frail older adults, infections can manifest with blunted inflammatory responses, leading to lower levels of traditional markers like CRP." (PMID 40407567, 2025). "Univariate logistic regression analysis revealed that TBSA, BI, infection markers (leukocytes, CRP, and PCT), and renal function indicators (Scr and BUN) were risk factors for death in severe burn patients during the shock stage (p < 0.01)." (PMID 40590000, 2025). "Upon evaluation in the emergency department, infection-related markers indicated a hypersensitive C-reactive protein (hs-CRP) level of 9.85 mg/L (normal range: 0–3 mg/L)." (PMID 40177421, 2025). "Although CRP is a classical acute-phase reactant synthesized in hepatocytes via IL-6, it is elevated not only in infections but also in malignancies, autoimmune diseases, and trauma." (PMID 40941711, 2025).
infection (continued). "In this regard, we recommend using CRP in conjunction with the WBC count as a biomarker for monitoring infection and treatment response." (PMID 41556000, 2025). "Of the 36 included studies, 13 (36.1%) reported to have incorporated current clinical biomarkers of infection, including CRP and PCT." (PMID 41149760, 2025). "CRP is considered as a biomarker of infection/inflammation, therefore the correlation of 25-HC level to CRP level was analyzed." (PMID 40621094, 2025). "Here, we investigated the relationship between changes in these CRP centiles, antibiotic prescribing, and patient outcomes in suspected infections." (PMID 40764898, 2025). "One week after surgery, infection markers including white blood cell count, neutrophil percentage, and CRP normalized, and renal function improved, preventing further damage to the right kidney." (PMID 41040639, 2025). "Patient 2 had a positive blood culture result that indicated an infection with Staphylococcus hominis, accompanied by significantly enhanced CRP." (PMID 40255402, 2025). "We thus assessed the plasma level of CRP in normal mice at 6, 12, 24, 36, 48, 60, and 72 h (hr) post i.v. infection with 106 CFU of Sp23F." (PMID 41214213, 2025). "GPs expressed a specific desire for POCTs to aid in diagnosing infections (eg, CRP and chlamydia), cardiac conditions (eg, troponin and B-type natriuretic peptide) and thrombotic disorders (eg, D-dimer)." (PMID 40436444, 2025). "Given that CRP levels return to baseline upon patient improvement, CRP is a useful marker to monitor infection status." (PMID 39886481, 2025). "All symptomatic UTIs patients had elevated leukocyte counts in urine tests, and 80% showed increased C-reactive protein (CRP) levels (≥ 50 mg/L), indicating the severity of the infection." (PMID 40452927, 2025). "In Mendelian randomisation analyses, interleukin-6 inhibition was predicted to have a large protective effect on the incidence of infection (OR 0.23; 95% CI 0.14–0.39 per standard deviation decrease in C- reactive protein)." (PMID 40819633, 2025). "CRP screening is a simple and reliable method for early detection of post-spinal surgery infections, with high predictive accuracy." (PMID 40342430, 2025). "The SII-PNI score demonstrated superior predictive ability (AUC: all-cause 0.80, CVD 0.80, infection 0.81) compared to SII, PNI, or CRP alone." (PMID 41348675, 2025). "During postoperative recovery, patients with infection tendencies need to be closely monitored for indicators including core body heat, leukocyte numbers, and concentrations of C-reactive protein (CRP)." (PMID 40710398, 2025). "Studies have shown that C-reactive protein (CRP) levels begin to rise 10-12 hours after the onset of infection." (PMID 40809608, 2025). "The cutoff value for the difference between the admission and previous CRP levels for predicting an infection that would hinder chemotherapy in all the patients was found to be ≥4.04 mg/dL." (PMID 40125102, 2025). "MBIs affect the physiological markers integral to immune function, such as those involved in inflammation (like CRP and IL-6) and improve the response to infection." (PMID 40281902, 2025). "IL-6 is a very important cytokine in the early host response to infection, and an increase in IL-6 precedes an increase in CRP." (PMID 39755760, 2025). "During episodes of tissue injury, infection, or inflammation, CRP synthesis is upregulated in hepatocytes." (PMID 41415536, 2025). "As a highly sensitive indicator of systemic inflammation and tissue damage, CRP levels can rapidly reflect changes in a patient’s condition following trauma, inflammation, or infection." (PMID 40333907, 2025). "Conventional diagnostic tools such as C-reactive protein (CRP) and erythrocyte sedimentation rate (ESR) lack specificity, particularly in low-grade or indolent infections." (PMID 41465792, 2025).